MIR190B (microRNA 190b)
Synonyms: hsa-mir-190b; MIRN190B; mir-190b
Gene: MicroRNA gene on chromosome 1 (154,193,665 to 154,193,743, reverse strand). Ensembl gene ENSG00000215938.
Gene Ontology:
Biological process: miRNA-mediated post-transcriptional gene silencing
Cellular component: RISC complex
Homologues: Orthologues: chimpanzee ptr-mir-190b (100% identical), macaque mml-mir-190b (99% identical), pig ssc-mir-190b (99% identical), guinea pig MIR190B (97% identical), dog MIR190B (92% identical), rat Mir190b (89% identical), tropical clawed frog xtr-mir-190 (75% identical), Drosophila melanogaster mir-190 (67% identical). Paralogues in human: MIR190A (77% identical).